E2F2 (E2F transcription factor 2)
Diseases named in the same sentence as E2F2 in open-access papers (continued):
Sharing a sentence is not in itself a finding about the gene and the disease.
colorectal adenocarcinoma (2 papers, 2018 to 2022). The most common type of colorectal carcinoma. "ROC analysis was applied to evaluate the effectiveness of E2F2 mRNA expression level to distinguish colorectal adenocarcinoma from normal tissues, which estimated AUC at 0.865 (95% CI: 0.784-0.946) in the GSE20916 data set." (PMID 35069909, 2022). "ROC analyses partially unveil that E2F2 can serve as a good predictive biomarker for discriminating colorectal adenocarcinoma and normal tissue." (PMID 35069909, 2022). "It has recently been reported that in colorectal adenocarcinoma, E2F2 expression at the tissue level was low." (PMID 30487158, 2018). "In order to furtherly determine the defferent expression level of E2F2 between colorectal tumor and normal tissues, we collected RNA-seq data and clinical information from 647 colorectal adenocarcinoma tissues and 51 colorectal normal tissues from the TCGA-COADREAD data sets." (PMID 35069909, 2022).
endometrial cancer (2 papers, 2015 to 2022). Primary or metastatic malignant neoplasm involving the endometrium (mucous membrane that lines the endometrial cavity). "This strong association of expression of E2F1, E2F2 and MYBL2 with ATAD2 is found in both CAHs, primary and metastatic endometrial cancer lesions, indicating that the expression of these genes are tightly linked in all stages of endometrial cancer." (PMID 26308378, 2015). "In 2015, a study observed that the expressions of E2F transcription factor 1 (E2F1), E2F transcription factor 2 (E2F2), and MYB proto-oncogene like 2 (MYBL2) are closely associated with ATAD2, which may be related to the invasion and progression of endometrial cancer." (PMID 36479043, 2022).
Fanconi anaemia (2 papers, 2021 to 2022). "In GSEA analysis, several pathways were significantly enriched corresponding to the E2F2 high expression phenotype, including ATR pathway, ATM signalling pathway, mismatch repair, base excision repair, homologous recomibination and Fanconi Anemia pathway." (PMID 35069909, 2022). "Several signal pathways were significantly enriched in high E2F2 expression group, including ATR pathway, ATM signalling pathway, mismatch repair, base excision repair, homologous recomibination and Fanconi Anemia pathway." (PMID 35069909, 2022). "GSEA disclosed that E2F2 was probably involved in several pathways, including ATR pathway, ATM signalling pathway, mismatch repair, base excision repair, homologous recomibination, Fanconi Anemia pathway, multicancer invasiveness signature, and cancer stem cells." (PMID 35069909, 2022). "Moreover, E2F2 is possibly involved in CRC tumorigenesis and development via modulating ATR pathway, ATM signalling pathway, mismatch repair, base excision repair, homologous recomibination, Fanconi Anemia pathway, multicancer invasiveness signature, cancer stem cells and immune infiltrating cells." (PMID 35069909, 2022).
Hepatitis B (2 papers, 2016 to 2021). "Next, using the DIANA-mirPath program, we investigated the mechanism by which miR-214/199a/199a* activates hepatitis B signaling, pathways in cancer and cell cycle, and found that 3 central cell-cycle promoting genes, E2F2, CDK3 and CDK6 was strikingly enriched in these predicted targets pathway." (PMID 26498144, 2016).
laryngeal carcinoma (2 papers, 2022 to 2023). Carcinoma that arises from the laryngeal epithelium. "In laryngeal cancer, lncRNA HOTAIR enhanced radioresistance via miR-454-3p/E2F2 axis." (PMID 35600868, 2022).
lymphoma (2 papers, 2009 to 2021). A malignant (clonal) proliferation of B- lymphocytes or T- lymphocytes which involves the lymph nodes, bone marrow and/or extranodal sites. "In contrast to the results seen with the E2f1 and E2f3 knockout animals, a deficiency of E2F2 dramatically accelerated the appearance of lymphoma." (PMID 19749980, 2009). "Our results indicate that E2f2 deficiency enhances the emergence of the “early-standard” form of lymphoma likely because the absence of E2F2 activity expands the population of cells that is the usual target for the oncogenic process in the Eμ-myc model." (PMID 19749980, 2009). "In addition, B lineage cells (B220+) isolated from E2f2+/+ and E2f2−/− lymphomas exhibited comparable rates of proliferation and apoptosis." (PMID 19749980, 2009). "Importantly, the spectrum and overall incidence of defects in the E2f2+/− and E2f2−/− lymphomas were very similar to that shown by the E2f2+/+ lymphomas." (PMID 19749980, 2009). "In addition, the E2f2+/− lymphomas showed no loss of heterozygosity demonstrating that E2F2 does not behave like a classic tumor suppressor in the Eμ-myc context (data not shown)." (PMID 19749980, 2009). "The work we present here provides clear evidence for an interaction between Myc and two E2Fs as seen by the effect on timing of tumor onset and the different characteristics of the lymphomas that arise in the absence of E2F2 or E2F4." (PMID 19749980, 2009). "Additional analysis revealed that a significant proportion of the E2f2−/− Eμ-myc lymphomas were not monoclonal." (PMID 19749980, 2009).
medulloblastoma (2 papers, 2021). A malignant, invasive embryonal neoplasm arising from the cerebellum. "According to the Cavalli dataset, the high expression of E2F1, E2F2 and E2F8 correlates with poor prognostic outcomes in medulloblastoma patients." (PMID 35011618, 2021). "Oliver’s team in research performed on a mouse model of medulloblastoma showed that MYCN promotes cell cycle gene expression; increase of MYCN expression level was there reported with significantly increased levels of E2F1 (3.7-fold), and E2F2 (6.1-fold)." (PMID 33430425, 2021).
myocardial infarction (2 papers, 2013 to 2025). Gross necrosis of the myocardium, as a result of interruption of the blood supply to the area, as in coronary thrombosis. "On the basis of these findings, lactylation driven transcription of genes such as E2f2 and Rfc3 may also be a potential therapeutic target for cardiomyocyte regeneration post-myocardial infarction (MI)." (PMID 41160759, 2025). "In this study, we sought to investigate the roles of E2F2 and E2F3 in EC proliferation and their functional impact on myocardial infarction (MI)." (PMID 23799044, 2013). "Here we investigated the roles of E2F2 and E2F3 in EC growth, angiogenesis, and their functional impact on myocardial infarction (MI)." (PMID 23799044, 2013).
nasopharyngeal carcinoma (2 papers, 2019 to 2024). A carcinoma arising from the nasopharyngeal epithelium. "Previous study indicated that CDKN2B-AS1 regulates E2F2 by sponging miR-98-5p to promote the proliferation, clone formation, and invasion of nasopharyngeal carcinoma (NPC) cells." (PMID 38436805, 2024).
nasopharyngitis (2 papers, 2019 to 2025). An inflammatory process that affects the nasopharynx. "We used immunohistochemical (IHC) and western blot methods to evaluate PPAR-γ and E2F2 expression and function in nonkeratinizing NPC and nasopharyngitis (NPG) tissue samples, as well as western blotting and CCK8 analyses in the NPC cell lines, CNE1 and CNE2." (PMID 31467515, 2019).
pancreatic ductal adenocarcinoma (2 papers, 2021). An infiltrating adenocarcinoma that arises from the epithelial cells of the pancreas. "M2 macrophages were associated with increased microvessel density in pancreatic ductal adenocarcinoma (PDAC) tissues, and exosomal miR-155-5p and miR-211-5p derived from M2 macrophages targeted E2F transcription factor 2 (E2F2) and promoted the angiogenic functions of mouse aortic ECs in vitro." (PMID 34966744, 2021).
Prostate tumor (2 papers, 2012 to 2022). "Prostate tumor specimens derived from patients display upregulated levels of E2F1 and E2F2, which are positively correlated with tumor malignancy, especially in the samples with the highest score in Gleason grade, and negatively correlated with disease-free survival." (PMID 36230876, 2022).
thymic epithelial tumors (2 papers, 2021 to 2022). "It is noteworthy that high incidence of thymic epithelial tumors was observed in E2F2 transgenic mice." (PMID 35844795, 2022). "Of note, E2F2 transgenic mice showed high incidence of thymic epithelial tumors." (PMID 34316028, 2021).
anaemia (1 paper, 2024). "Since HO-1 catalysers the degradation of haem, the reduction of expression of E2F2 in-flight may be one of the contributing factors resulting in space anaemia." (PMID 38862545, 2024).
arrhythmogenic right ventricular cardiomyopathy (1 paper, 2023). "The GSEA enrichment analysis demonstrated that E2F2 is closely associated with arrhythmogenic right ventricular cardiomyopathy, cell circle, dilated cardiomyopathy, DNA replication, hypertrophic cardiomyopathy hcm, and spliceosome." (PMID 36923953, 2023).
asbestosis (1 paper, 2023). A lung disorder caused by inhalation of asbestos fibers. "E2F2 rs2075995 was also associated with higher serum calretinin level among subjects with asbestosis." (PMID 38038422, 2023). "In subjects with asbestosis, carriers of at least one polymorphic E2F2 rs2075995 A allele had higher calretinin than carriers of two wild-type alleles in the additive model (P = 0.049) and dominant model (P = 0.017)." (PMID 38038422, 2023).
autoimmune disease (1 paper, 2021). A disorder resulting from loss of function or tissue destruction of an organ or multiple organs, arising from humoral or cellular immune responses of the individual to their own tissue constituents. "SPIB, as well as E2F2, GATA4 and TCF7L2 have been associated with other autoimmune diseases through differential gene expression and genetic polymorphisms, respectively." (PMID 33915751, 2021).
B-cell lymphoma (1 paper, 2019). "The E2F2 and E2F4 factors bind to the E2 recognition motif and are involved in cell cycle processes, DNA damage response and regulate TERT transcription in human B-cell lymphoma." (PMID 31888467, 2019).
behavioral disorders (1 paper, 2025). "Notably, genes associated with immune modulation and inflammation (e.g., Dusp1, Lrrc39, E2f2), neuroplasticity and memory (e.g., Cpeb3, Efnb3), and behavioral disorders (e.g., Pla2g4c) exhibited substantial changes." (PMID 40285614, 2025).
brain glioma (1 paper, 2018). A malignant glioma that involves the brain. "Our study extends these findings by showing that miR-214 targeting of E2F2 inhibits the proliferation of human brain glioma cells through a PPARα-regulated pathway." (PMID 29862267, 2018).
Burkitt lymphoma (1 paper, 2009). A rare form of malignant mature B-cell non-Hodgkin lymphoma. "The majority of early-onset tumors, either from E2f2+/+ or E2f2−/− mice, featured high mitotic indices and extensive apoptosis with tingible body macrophages and a starry sky appearance similar to that of human Burkitt lymphoma (data not shown)." (PMID 19749980, 2009).
colon adenocarcinoma (1 paper, 2022). "The E2F2 mRNA expression in COAD (colon adenocarcinoma) and READ (rectum adenocarcinoma) was shown to be significantly downregulated compared with their normal tissues." (PMID 35069909, 2022). "The results also illustrated that E2F2 was prominently downregulated in colon adenocarcinoma compared with nomal tissues (p < 0.001)." (PMID 35069909, 2022).
COVID-19 (1 paper, 2022). A disease caused by infection with severe acute respiratory syndrome coronavirus 2. "GFI1, ZNF90, E2F8, E2F2, and EZH2 were also specific to exhausted T cells and may play a vital role in TEX in severe COVID-19." (PMID 35694714, 2022).
cyst (1 paper, 2021). A sac-like closed membranous structure that may be empty or contain fluid or amorphous material. "Increased KLF5 and E2F2 expression levels were observed in tumor tissues, especially in the palisading epithelium and the cyst wall." (PMID 35155179, 2021).
depression (1 paper, 2022). "In summary, our data demonstrated that MOs alleviate experimental depression and inflammation via the E2F2-mediated MyD88/PI3K signalling pathway." (PMID 36052143, 2022).
dissection (1 paper, 2021). The separation and isolation of tissues for surgical purposes, or for the analysis or study of their structures. "At first, although it has been shown that E2F2, IGF1R, and BDNF can cause arterial-related diseases, there is no research to prove the relationship between aortic dissection and these target gene." (PMID 34620091, 2021).
endometriosis (1 paper, 2018). The growth of functional endometrial tissue in anatomic sites outside the uterine body. "Their subsequent functional experiments revealed that miR-196b can inhibit proliferation and induce apoptosis in endometriotic stromal cells, which led us to hypothesize that E2F2 might also play important roles in endometriosis by targeting miR-196b." (PMID 29357938, 2018).
ependymoma (1 paper, 2021). A WHO grade II, slow growing tumor of children and young adults, usually located intraventricularly. "Among them inverse correlations (r > −0.61) were noted in the ependymoma group for miR-106b-MYCC, miR-106b-MYCN, miR-106b-E2F2, miR-106b-E2F3, miR-93-MYCN, miR-25-MYCN, miR-25-E2F2, miR-25-E2F3, i.e., members of the miR-106b-25 cluster." (PMID 33430425, 2021). "In ependymomas, gene expression negatively correlated with the expression of cluster members, e.g., miR-106b-MYCC r = −0.42, miR-106b-MYCN r = −0.61, miR-106b-E2F2 r = −0.51, miR-106b-E2F3 r = −0.58, miR-93-MYCN r = −0.47, miR-25-MYCN r = −0.47, miR-25-E2F2 r = −0.49, miR-25-E2F3 r = −0.52." (PMID 33430425, 2021).
Ewing sarcoma (1 paper, 2013). A small round cell tumor that lacks morphologic, immunohistochemical, and electron microscopic evidence of neuroectodermal differentiation. "Because IER3 is a modulator of apoptosis through TNFalpha or FAS-signaling, the balance between its repression (through MYC, E2F2 and E2F5 that are EWS-FLI1 induced and therefore disease specific) and activation (through NFkB) may be of particular interest in Ewing sarcoma." (PMID 23935076, 2013).
HCMV infection (1 paper, 2011). "E2F1, but not E2F2 or E2F3, promotes the accumulation of γH2AX during HCMV infection or IE protein expression." (PMID 21589897, 2011).
head and neck cancer (1 paper, 2024). A primary or metastatic malignant neoplasm affecting the head and neck. "A limited number of studies in the literature have investigated the role of E2F1 and E2F2 SNPs in head and neck cancer." (PMID 38360622, 2024).
Hepatic steatosis (1 paper, 2014). Steatosis is a term used to denote lipid accumulation within hepatocytes. "Previous work has shown that the massive hepatic steatosis occurring during the first 3–4 days of regeneration in WT mice persisted over 7 days in E2F2 knockout mice, suggesting a defective mobilization of stored TAG in this condition." (PMID 25396754, 2014). "Our study also revealed that E2F2 determines the duration of hepatectomy-induced hepatic steatosis." (PMID 25396754, 2014).
insulin-dependent diabetes (1 paper, 2008). "E2f2 is the best candidate in this region considering that mice deficient for both E2F1 and E2F2 develop nonautoimmune, insulin-dependent diabetes with high penetrance." (PMID 19471607, 2008).
ischemic heart disease (1 paper, 2013). "Thus, E2F3 promotes while E2F2 suppresses ischemic cardiac repair through corresponding changes in EC proliferation; and differential targeting of specific E2F members may provide a novel strategy for therapeutic angiogenesis of ischemic heart disease." (PMID 23799044, 2013).
leukopenia (1 paper, 2017). "Repressing E2f3 in E2f1−/−; E2f2−/− doubly-deficient mice triggered profound collapse of bone marrow, together with the onset of leukopenia, thrombocytopenia and progressive erythrocytopenia, with corresponding decreases in lymphocyte and myeloid cell populations." (PMID 28855541, 2017). "By three weeks post tetracycline withdrawal, E2f1−/−; E2f2−/−; E2f3TRE/TRE; β-actin-tTS mice exhibited severe leukopenia and thrombocytopenia." (PMID 28855541, 2017).
liver disease (1 paper, 2024). "To summarize, our analysis has clarified the function of macrophage E2F2 in steatohepatitis and has demonstrated a negative correlation between the expression of E2F2 and the severity of liver disease in MASH patients." (PMID 39465673, 2024).
liver fibrosis (1 paper, 2024). "The findings showed that liver fibrosis severity increased in the mice on either diet, and this effect was exacerbated by the deficiency of macrophage E2F2." (PMID 39465673, 2024). "Further investigations demonstrated that the absence of E2F2 in macrophages contributed to the activation of HSCs and the progression of liver fibrosis in MASH." (PMID 39465673, 2024).
Lynch syndrome (1 paper, 2013). An autosomal dominant hereditary neoplastic syndrome characterized by the development of colorectal carcinoma and a high risk of developing endometrial carcinoma, gastric carcinoma, ovarian carcinoma, renal pelvis carcinoma, and small intestinal carcinoma. "Lynch syndrome tumors showed up-regulation of 1129 genes, e.g. genes involved in G1/S transition (CCNE, CCNH, E2F2 and CDK2), DNA replication (CDC45, RPA1, RFC5, MCM4 and POLD3) and chromosomal organization and mitosis (CCNB2, MLF1IP, CASC5, KIF2C and PLK4), which is in line with previous findings." (PMID 23951239, 2013).
male infertility (1 paper, 2023). The inability of the male to effect fertilization of an ovum after a specified period of unprotected intercourse. "DNM3OS was found to regulate the apoptosis and senescence of spermatogonia by providing miR-214-5p and decreasing E2F2 expression, suggesting it as a novel target for gene therapy of male infertility." (PMID 38152068, 2023).
metastasis (1 paper, 2024). The spread or migration of cancer cells from one part of the body (where they first appeared) to another. "Moreover, significant findings of E2F2 rs2075993, rs3820028 involvement in LSCC differentiation, and the impact of E2F1 rs3213180 on lymph node metastasis were determined." (PMID 38360622, 2024).
oropharyngeal cancer (1 paper, 2021). Carcinoma, predominantly squamous cell, arising from the epithelial cells of the oropharynx. "In another report, miR496 is downregulated by Human papillomavirus, notably type 16 and inhibit the post-transcriptional control of the transcription factor E2F2 in oropharyngeal cancer." (PMID 34514167, 2021).
osteoporosis (1 paper, 2024). A condition of reduced bone mass, with decreased cortical thickness and a decrease in the number and size of the trabeculae of cancellous bone (but normal chemical composition), resulting in increased fracture incidence. "Further studies revealed that miR-31a-5p promotes the expression of senescence-associated markers by inhibiting E2F transcription factor 2 (E2F2) activity, which leads to increased osteoclast activity and ultimately results in osteoporosis." (PMID 39595531, 2024).
pancreatic adenocarcinoma (1 paper, 2020). "In addition, ONCOMINE analysis revealed no significant contrast in the transcriptional levels of E2F2, E2F4, and E2F6 between pancreatic adenocarcinoma and normal samples." (PMID 33604289, 2020).
serous ovarian carcinomas (1 paper, 2016).
steatosis (1 paper, 2024). Increased lipid within the cytoplasm of cells. "E2F2 levels were considerably lower in the livers of people with simple steatosis or MASH compared to those without steatosis, which is consistent with our findings in mice." (PMID 39465673, 2024).
stomach adenocarcinoma (1 paper, 2021). "Further subgroup analysis of various clinicopathological features of TCGA-stomach adenocarcinoma (STAD) samples in the UALCAN database consistently showed that the E2F2 mRNA level was elevated." (PMID 34091441, 2021). "The expression of E2F2 mRNA in stomach adenocarcinoma was higher than that in paracancerous normal tissues." (PMID 34091441, 2021).